IMPG2 (interphotoreceptor matrix proteoglycan 2)
Description:
Chondroitin sulfate- and hyaluronan-binding proteoglycan involved in the organization of interphotoreceptor matrix; may participate in the maturation and maintenance of the light-sensitive photoreceptor outer segment. Binds heparin.
Synonyms: Spacrcan; IPM200; RP56; VMD5
Tractability: Antibody: UniProt places it where antibodies can reach, with high confidence; its Gene Ontology location is reachable by antibodies, with high confidence; UniProt predicts a signal peptide or a membrane-spanning region.
Gene: Protein-coding gene on chromosome 3 (101,222,546 to 101,320,575, reverse strand). Ensembl gene ENSG00000081148.
Subcellular location: Photoreceptor outer segment membrane; Photoreceptor inner segment membrane; Secreted, extracellular space, extracellular matrix, interphotoreceptor matrix
Gene Ontology:
Molecular function: extracellular matrix structural constituent; heparin binding; hyaluronic acid binding
Biological process: visual perception
Cellular component: gel phase of interstitial matrix; receptor complex; extracellular matrix; interphotoreceptor matrix
Genetic constraint (gnomAD): Loss-of-function variants: 72 observed, 113.29 expected, observed/expected ratio (o/e) 0.64, 90% interval 0.52 to 0.77. The upper end of that interval is the gene's LOEUF score, 0.77, which puts it in group 3 of 6, group 1 being the genes least tolerant of losing a copy. Missense variants: 1,329 observed, 1,427.2 expected, observed/expected ratio (o/e) 0.93, 90% interval 0.89 to 0.97. Synonymous variants: 483 observed, 509.88 expected, observed/expected ratio (o/e) 0.95, 90% interval 0.88 to 1.02.
Gene-disease validity (ClinGen):
ClinGen rates the evidence that IMPG2 causes each of these diseases.
IMPG2-related recessive retinopathy (autosomal recessive): Definitive. Any retinopathy caused by bi-allelic variants in the IMPG2 gene.
Homologues: Orthologues: chimpanzee IMPG2 (99% identical), macaque IMPG2 (97% identical), dog IMPG2 (79% identical), rabbit IMPG2 (76% identical), pig IMPG2 (75% identical), guinea pig IMPG2 (74% identical), mouse Impg2 (71% identical), rat Senp7 (71% identical), tropical clawed frog impg2 (32% identical), zebrafish impg2b (19% identical), zebrafish impg2a (15% identical). Paralogues in human: IMPG1 (20% identical).
Diseases named in the same sentence as IMPG2 in open-access papers:
IMPG2 is named in the same sentence as 27 diseases in open-access papers, as found by Europe PMC text mining. Sharing a sentence is not in itself a finding about the gene and the disease. The quoted sentences say what the papers report.
retinitis pigmentosa (10 papers, 2014 to 2025). Retinitis pigmentosa (RP) is an inherited retinal dystrophy leading to progressive loss of the photoreceptors and retinal pigment epithelium and resulting in blindness usually after several decades. "Mutations in IMPG1 or IMPG2 are linked to retinal diseases such as retinitis pigmentosa (RP) and vitelliform macular dystrophy (VMD), yet the specific mutations responsible for each condition remain undefined." (PMID 39858590, 2025). "Biallelic mutations in interphotoreceptor matrix proteoglycan 2 (IMPG2) in humans cause retinitis pigmentosa (RP) with early macular involvement, albeit the disease progression varies widely due to genetic heterogeneity and IMPG2 mutation type." (PMID 37975905, 2024). "Interphotoreceptor matrix proteoglycan 2 (IMPG2) mutations are associated with retinitis pigmentosa (RP) and macular dystrophy." (PMID 39546296, 2024). "In humans, biallelic IMPG2 mutations cause retinitis pigmentosa (RP), whereas monoallelic IMPG2 mutations are linked to adult-onset vitelliform macular dystrophy (AVMD)." (PMID 37975905, 2024). "In F4, the compound heterozygous variants p.[R964*];[W758*] were observed in IMPG2 with a retinitis pigmentosa (RP) phenotype." (PMID 33634125, 2021). "Variants in IMPG2 are associated with a form of retinitis pigmentosa." (PMID 24786987, 2014). "In our cohort, we demonstrate three distinct phenotypes as follows: pattern dystrophy in both the monoallelic IMPG1 cases, maculopathy (PD/AVMD) in the monoallelic IMPG2 cases, and retinitis pigmentosa with early maculopathy in biallelic IMPG2 cases." (PMID 41465146, 2025). "The diagnosis of early-onset retinitis pigmentosa in this patient was even earlier than observed in the PRPH2-related patients with RP of our cohort, which seems to be a compatible phenotype with IMPG2 causative variants." (PMID 38474159, 2024).
vitelliform macular dystrophy (9 papers, 2017 to 2025). A rare genetic disorder characterized by macular degeneration in the retina resulting in progressive loss of central vision with retention of the peripheral vision. "Mutations of IMPG1 and IMPG2 cause vitelliform macular dystrophies and autosomal-recessive RP, respectively." (PMID 40450528, 2025). "IMPG2 has previously been associated with autosomal recessive RP and vitelliform macular dystrophy (VMD) in humans and is therefore a strong candidate gene for canine PRA." (PMID 32894063, 2020). "In this study we have identified a series of novel mutations in the IMPG1/IMPG2 genes and provide supportive evidence for their causativity in the development of vitelliform macular dystrophy." (PMID 28644393, 2017). "This demarcation between mutations linked to RP or vitelliform macular dystrophy in IMPG1 is not mirrored in IMPG2, where mutations within and outside the SEA domains can generate either pathology." (PMID 36109576, 2022).
retinal disease (6 papers, 2017 to 2025). "The role of IMPG2 in retinal photoreceptors and its association with human retinal disease therefore makes it a strong candidate gene for canine retinal disorders." (PMID 32894063, 2020). "IMPG-2, a gene mainly associated with retinal disease, was upregulated in chemoresistant osteosarcoma samples in our study, but more studies involving IMPG-2 and cancer needed to be conducted." (PMID 29850522, 2018). "Hitti-Marlin and colleagues mapped a LINE-1 insertion upstream of the IMPG2 gene in a canine retinal disease." (PMID 38682429, 2024). "We suggest that it may be possible to extend this approach to preclinical research in which therapeutics (e.g., gene therapy) are evaluated for the treatment of retinal disease, such as IMPG2-RP." (PMID 37975905, 2024). "IMPG2 has previously been implicated in human retinal disease; however, until now no canine PRAs have been associated with this gene." (PMID 32894063, 2020). "Their father was diagnosed with VMD not before the age of 62 and they may develop retinal disease later in life consistent with a rather late disease onset for symptomatic carriers of known C-terminal IMPG2 missense mutations." (PMID 28644393, 2017).
cone-rod dystrophy (4 papers, 2020 to 2023). Inherited retinal dystrophies that belong to the group of pigmentary retinopathies. "Biallelic variants in IMPG2 have been shown to underlie recessive childhood-onset rod-cone dystrophy with early macular involvement in several families." (PMID 33634125, 2021). "Mutations in IMPG2 result in autosomal recessive RP and childhood-onset rod-cone dystrophy with early macular involvement in humans." (PMID 32894063, 2020). "Pseudodominant inheritance has already been documented in retinal disorders, including congenital stationary night blindness (CSNB) with alterations in the GRM6 gene, in patients with RP related to IMPG2 variants, or in cone-rod dystrophy and Stargardt disease with ABCA4 pathogenic variants." (PMID 36832217, 2023).
retinal degeneration (4 papers, 2008 to 2024). Degeneration of the retina. "Unravelling the molecular processes linking mutations in the IMPG1 and IMPG2 genes to retinal degeneration will be an important task for future experiments." (PMID 28644393, 2017). "Thus, IMPG2, resulting in matrix alteration, will cause retinal degeneration." (PMID 37709773, 2023). "Elevated IMPG2 mRNA levels early in retinal degeneration might also be circumstantial evidence of the importance of chondroitin sulfate proteoglycans in the IPM to maintain functional photoreceptors." (PMID 19050768, 2008). "In the present work, we showed that NGC, IMPG2, and CD44 mRNA expression was induced during retinal degeneration in Rpe65−/− mice." (PMID 19050768, 2008). "An increased mRNA expression of the genes coding for the extracellular matrix proteins neuroglycan C (NGC), interphotoreceptor matrix proteoglycan 2 (IMPG2), and CD44 antigen (CD44) has been observed during retinal degeneration in mice with a targeted disruption of the Rpe65 gene (Rpe65−/− mouse)." (PMID 19050768, 2008).
medulloblastoma (3 papers, 2023 to 2024). A malignant, invasive embryonal neoplasm arising from the cerebellum. "The rest 29 antigens were all expressed by TAAs and NEUROG1 and IMPG2 were expressed by over 90% tumors, making them the most suitable antigen targets for Group 3 medulloblastoma." (PMID 39160595, 2024). "Furthermore, we identified retina specific interphotoreceptor matrix proteoglycan 2 (IMPG2), phosducin (PDC) and prominin 1 (PROM1) as upregulated genes in the RB tumor group, which are all related to CRX expression in medulloblastoma." (PMID 39695086, 2024).
autosomal recessive retinitis pigmentosa (2 papers, 2017 to 2023). Autosomal recessive retinitis pigmentosa (RP) is an autosomally recessive inherited retinal dystrophy leading to progressive loss of the photoreceptors and retinal pigment epithelium and resulting in blindness usually after several decades. "Homozygous or compound heterozygous nonsense, frameshift or splice site mutations in the IMPG2 gene causing loss of IMPG2 function have repeatedly been described in patients with autosomal recessive retinitis pigmentosa (RP)." (PMID 28644393, 2017). "Another missense variant in the IMPG2 gene (OMIM: #607056) associated with autosomal dominant macular dystrophy type 5 (MIM: #616152) and autosomal recessive Retinitis Pigmentosa (OMIM: #613581) was found in both affected individuals." (PMID 37895187, 2023).
Inherited Retinal Dystrophies (2 papers, 2023 to 2025). "This study supports the association of IMPG1 and IMPG2 mutations with retinal dystrophies and implies the prevalence of these mutations in IRDs in the Caucasian population for the first time." (PMID 39858590, 2025). "Recent studies have found the presence of nonsense mutations in the interphotoreceptor matrix proteoglycan 2 (IMPG2) gene in patients affected by retinal dystrophies." (PMID 37470839, 2023). "However, the patient’s EOG results were normal, a finding inconsistent with Best disease but more indicative of IMPG2-associated retinal dystrophy." (PMID 39858590, 2025). "This raises intriguing hypotheses about its possible role(s) during retinal maturation, laying the groundwork for the generation of most needed models for the study of IMPG2-related inherited retinal dystrophies." (PMID 37470839, 2023).
Macular dystrophy (2 papers, 2021 to 2024). Macular dystrophy is a nonspecific term for retinal degeneration, generally confined to the macula, usually presumed of genetic origin. "In gene IMPG2 (also dominant) we prioritized one other VUS (NM_016247.3: c.2872A > G) in a Macular Dystrophy case, also selected by geneticist- and predictor rule, that cosegregates with the disease in the affected father, and is classified as likely pathogenic in VarSome." (PMID 33623043, 2021).
Bull's eye maculopathy (1 paper, 2017). Progressive maculopathy characterized by concentric regions of hyper- and hypopigmentation, with an initial foveal sparing and whose appearance is said to resemble the central target of a dart board. "A recent report about patients with IMPG2-associated RP revealed that three quarters of the patients (n = 13) had profound macular abnormalities including bull’s eye maculopathy and macular atrophy." (PMID 28644393, 2017).
diabetic retinopathy (1 paper, 2012). "From this perspective, the identification of photoreceptor-specific changes in arrestin, Impg2, and Trpm1 raises the further possibility of a contribution by photoreceptors to diabetic retinopathy." (PMID 22605924, 2012). "Specifically, alternative splicing of arrestin (Arr), interphotoreceptor matrix proteoglycan (Impg2), and transient receptor membrane potential cation channel provide tentative evidence for the effects of diabetic retinopathy on the activity and integrity of photoreceptor cells in the retina." (PMID 22605924, 2012).
glaucoma (1 paper, 2021). Increased pressure in the eyeball due to obstruction of the outflow of aqueous humor. "Interestingly, mass spectrometry of the probes revealed a regulation of certain proteins after S100B immunization, which are not directly linked to glaucoma or RGCs, such as IMPG1 and IMPG2." (PMID 35053014, 2021).
Gliosis (1 paper, 2024). Gliosis is the focal proliferation of glial cells in the central nervous system. "Gliosis has been previously observed in Impg2 knockout mice and in other animal models in response to retinal damage." (PMID 37975905, 2024).
myopia (1 paper, 2025). "Other notable myopia associations include RPGR (~80% of XLRP, −2.6–−9D), OAT (gyrate atrophy, −9D), RP1 (~1% of ARRP, −5.5D; 5–7% of ADRP, ~−1D) and IMPG2 (~−4D)." (PMID 41465105, 2025).
Usher syndrome type 1B (1 paper, 2025). "IMPG2-mutant ROs showed photoreceptor outer segment abnormalities, while MYO7A-deficient ROs, associated with Usher syndrome type 1B, did not exhibit overt photoreceptor death." (PMID 39422807, 2025).
uveitis (1 paper, 2016). An inflammatory process affecting a part of or the entire uvea. "Autoantibody reactivity towards a second antigen representing an extracellular region of IMPG2 was in contrast present in serum from uveitis patients." (PMID 27930731, 2016). "Autoantibodies towards IMPG2 (antigen number 205) were prevalent with highly positive titres in two patient samples with (n)pAIR (8.3%) and with lower prevalence in uveitis patients (2.0%)." (PMID 27930731, 2016).
retinal disorder (4 papers, 2014 to 2025). Any disease or disorder of the retina. "Herein we characterise the phenotypic and genotypic features of patients with IMPG1/IMPG2 retinopathy and report novel variants." (PMID 41465146, 2025). "The identification of novel variants expands the known genetic landscape of IMPG1 and IMPG2 retinopathies." (PMID 41465146, 2025). "This supports the hypothesis that haploinsufficiency may be the underlying mechanism in IMPG2 retinopathy due to the prevalence of truncating IMPG2 variants in both RP and maculopathy phenotypes, and the absence of these variants in control populations." (PMID 41465146, 2025). "Our patients did not undergo FA, ICGA, or enhanced depth imaging (EDI) OCT, which limits our ability to draw clear conclusions about the relationship between pachychoroid and the adult vitelliform/PD phenotype in IMPG1 and IMPG2 retinopathy." (PMID 41465146, 2025). "EDT testing was not performed in our study but other studies have shown normal EOG but the mfERG amplitudes can be reduced in the central rings in IMPG1 and IMPG2 retinopathy." (PMID 41465146, 2025). "Haploinsufficiency has been proposed as an underlying mechanism for maculopathy phenotypes in monoallelic IMPG2 retinopathy cases." (PMID 41465146, 2025). "The current literature on variability in the phenotype and appearance of IMPG1 and IMPG2 retinopathy remains limited with only small cohort studies having been reported to date." (PMID 41465146, 2025). "This study adds to the phenotypic characterisation of IMPG1 and IMPG2 retinopathies, describing phenotypic variability and exploring genotype–phenotype correlations hereby adding to the current knowledge base and thus aiding diagnosis." (PMID 41465146, 2025). "Future studies with longer follow up with familial surveys and segregation studies are required to accurately characterise the natural history of IMPG1 and IMPG2 retinopathies and also identify penetrance in monoallelic individuals." (PMID 41465146, 2025). "These insights improve our ability to diagnose IMPG1 and IMPG2 retinopathy and have important implications for genetic testing, clinical management, and potential future therapeutic strategies." (PMID 41465146, 2025). "There were 5 monoallelic IMPG2 retinopathy patients with a maculopathy phenotype, of whom 1 had PD and 4 had AVMD." (PMID 41465146, 2025). "Herein we report the phenotypic spectrum and genotypes of thirteen patients with either IMPG1 or IMPG2 retinopathy." (PMID 41465146, 2025). "This study included 13 patients with IMPG related retinopathy, including 2 IMPG1 (1 male, 1 female) and 11 IMPG2 cases (7 male, 4 female)." (PMID 41465146, 2025).
tumor (4 papers, 2023 to 2026). "Furthermore, we developed a prognostic nomogram based on IMPG2, BNC2, PAPPA2, ITGBL1and UNC13C expression levels in tumor cells to predict survival outcomes." (PMID 42157926, 2026).
IMPG2 also shares sentences with these, for which no sentence is quoted: cancer (2 papers); retinal dystrophies (2); Bardet-Biedl syndrome (1); congenital stationary night blindness (1); developmental and epileptic encephalopathy (1); keratoconus (1); Onset (1); osteosarcoma (1); Stargardt disease (1).